C1R (complement C1r)
Diseases named in the same sentence as C1R in open-access papers (continued):
Sharing a sentence is not in itself a finding about the gene and the disease.
preeclampsia (3 papers, 2021 to 2024). Preeclampsia is a hypertensive disorder of pregnancy that is characterized by new-onset hypertension with proteinuria presenting after 20 weeks of gestation, and depending on mild or severe forms may initially present with severe headache, visual disturbances, and hyperreflexia. "C1r expression is decreased in the implantation site of the preeclampsia model, and C2 deficiency results in thrombocytopenia during early pregnancy." (PMID 34827915, 2021). "Blood samples were taken from all patients with preeclampsia to measure signal peptide complement C1r/C1s, Uegf, and Bmp1, and epidermal growth factor-containing protein 1 levels at the time of hospitalization." (PMID 38451587, 2024). "In multivariate analysis, signal peptide complement C1r/C1s, Uegf, and Bmp1, and epidermal growth factor-containing protein 1 was determined as an independent predictor for preeclampsia (OR: 1.678, 95%CI 1.424-1.979, p<0.001)." (PMID 38451587, 2024). "C1r is undetected in the implantation site of the preeclampsia model, suggesting that C1r expression in the implantation site is beneficial for successful pregnancy in mice." (PMID 34827915, 2021). "Additionally, complement-associated genes were reduced in early-onset preeclampsia compared to healthy placentas (P=0.007), including complement 7 (C7), complement C1q A chain (C1QA), complement 2 (C2), and complement C1r (C1R)." (PMID 34992598, 2021).
viral infection (3 papers, 2022 to 2025). "Increased levels of apolipoproteins A-I, A-IV, C-IV, and M during IM imply associations with viral infection, while complement system proteins (C1q, C1r, and C8 gamma chain) are also elevated, reflecting their role in the immune response and viral clearance." (PMID 38921769, 2024). "The CXCL10/11high basal cells also had upregulated mRNA encoding for complement components (C1R and C1S), MHC class I (HLA-A, HLA-B, HLA-C, and B2M), and metalloproteases MMP2 and MMP13, the latter reducing repair during viral infection in bronchial epithelial cells." (PMID 40980495, 2025).
acute myeloid leukemia (2 papers, 2015 to 2022). Acute myeloid leukemia (AML) is a group of neoplasms arising from precursor cells committed to the myeloid cell-line differentiation. "DNA-methylation of C1R is significantly correlated with overall survival in acute myeloid leukemia." (PMID 35203526, 2022).
autoimmune disease (2 papers, 2016 to 2018). A disorder resulting from loss of function or tissue destruction of an organ or multiple organs, arising from humoral or cellular immune responses of the individual to their own tissue constituents. "In contrast, complete deficiency of C1r or C1s caused by homozygous C1R- or C1S-null mutations causes a lupus-erythematosus-like syndrome with increased susceptibility to infections and increased risk of developing autoimmune diseases." (PMID 27745832, 2016).
cyst (2 papers, 2021 to 2022). A sac-like closed membranous structure that may be empty or contain fluid or amorphous material. "C1q and C1r are up-regulated in the brain with high cyst burden." (PMID 34408631, 2021).
endometriosis (2 papers, 2023 to 2025). The growth of functional endometrial tissue in anatomic sites outside the uterine body. "Multi-omics analysis has revealed that up-regulated expression of complement (C1S, C1QA, C1R and C3) was positively correlated with tissue factor in endometriosis." (PMID 38012607, 2023).
influenza (2 papers, 2021 to 2022). An acute viral infection of the respiratory tract, occurring in isolated cases, in epidemics, or in pandemics; it is caused by serologically different strains of viruses (influenzaviruses) designated A, B, and C, has a 3-day incubation period, and usually lasts for 3 to 10 days. "Differently, in early COVID-19 infection, down-regulation of complement and coagulation cascades has been observed (C1R, C7) compared to influenza infection [TE88]." (PMID 34876157, 2021). "Virus-related diseases (SARS-CoV-2 high viral load and influenza) in particular showed significant changes on the expression of lung epithelial-cell-related transcripts (i.e., ACTB, C1R, and FN1); such changes are known markers of lung-injury gene signatures." (PMID 35233546, 2022).
Lyme disease (2 papers, 2023 to 2025). Lyme disease (named after the towns in the USA where the disease was first identified) is a bacterial infection caused by Borrelia burgdorferi. "This analysis provides the foundation for pointed structure-guided mechanistic characterization of other C1r inhibitors—as well as Fn binding—across Lyme disease and tick-borne relapsing fever (TBRF) spirochetes." (PMID 40705830, 2025). "One borrelial lipoprotein, BBK32, protects the Lyme disease spirochete from complement-mediated attack via an alpha helical C-terminal domain that interacts directly with the initiating protease of the classical complement pathway, C1r." (PMID 37380082, 2023).
rheumatoid arthritis (2 papers, 2014 to 2019). A chronic, systemic autoimmune disorder characterized by inflammation in the synovial membranes and articular surfaces. "Although it is a multifactorial disease, there is an overwhelming clinical evidence showing that homozygous deficiency in any of the classical pathway proteins – C1q, C1r, C1s, C4, and C2 – predisposes an individual to develop SLE and other autoimmune diseases such as rheumatoid arthritis (RA)." (PMID 25018754, 2014).
squamous cell carcinoma (2 papers, 2022). A carcinoma arising from squamous epithelial cells. "C1R, which was identified to decrease overall survival for patients with ALL, AML, and RT when upregulated, has been reported to promote the progression of squamous cell carcinoma when elevated." (PMID 36497424, 2022).
temporal lobe epilepsy (2 papers, 2015 to 2024). A localization-related (focal) form of epilepsy characterized by recurrent seizures that arise from foci within the temporal lobe, most commonly from its mesial aspect. "Several apolipoproteins (APOA1, APOD, and APOA4), serpin protease inhibitors (SERPINA3, SERPINF1, etc.), complement components (C9, C8, and C1R), and a total of 42 proteins were found to be significantly upregulated in the temporal lobe epilepsy group." (PMID 39063177, 2024). "However, activation of the complement system, i.e. upregulation of complement mediators including C1qa and C1r, has been reported in both experimental and human temporal lobe epilepsy and is thought to contribute to neuronal hyper-excitability and seizures." (PMID 26684451, 2015).
type 2 diabetes (2 papers, 2021 to 2025). "Using proteomic research methods, 2D electrophoresis and mass spectrometric analysis, increased concentrations of the complement system sub-components C1r, C3 and C4-B, α-1-antitrypsin and vitronectin were detected in patients with type 2 diabetes mellitus compared to the control group." (PMID 34948066, 2021).
actinic keratosis (1 paper, 2024). A precancerous lesion of the skin composed of atypical keratinocytes. "Serine proteases, C1r, and C1s, were found to be significantly overexpressed in RDEB-associated and invasive sporadic cSCCs, relative to cSCC in situ, actinic keratosis, and normal skin." (PMID 38769503, 2024).
Allergy (1 paper, 2023). An allergy is an immune response or reaction to substances that are usually not harmful. "Together we report both the coagulation cascade, specifically the genes F13A1, SERPINE1 and C1R, and the CCR10/CCL27 axis, as candidate pathways used by IgE-binding monocytes in the mechanism of allergy." (PMID 37193769, 2023).
aneurysm (1 paper, 2022). Bulging or ballooning in an area of an artery secondary to arterial wall weakening. "Since C1R is an aneurysm-associated gene, we hypothesized that complement activation could enhance aortopathy in MFS." (PMID 36279189, 2022). "Human aortic samples were collected from MFS and non-MFS aneurysm patients to study complement factor gene expression C1R, C1S, C3AR1, and C5AR1 and SMC gene ACTA2." (PMID 36279189, 2022).
arrhythmogenic right ventricular cardiomyopathy (1 paper, 2016). "Besides, some other ones were correlated with arrhythmogenic right ventricular cardiomyopathy (e.g. ACTN4, CTNNA1 and ITGB5), as well as complement and coagulation cascades (e.g. C1R and C1S)." (PMID 27613243, 2016).
Arthritis (1 paper, 2023). Inflammation of a joint. "In dogs with arthritis, active forms of C1r and C1s, along with reduced concentrations of IGFBP-5, IGFBP-3 and IGF-1, were present in their synovial fluid." (PMID 38002958, 2023).
Cachexia (1 paper, 2020). Severe weight loss, wasting of muscle, loss of appetite, and general debility related to a chronic disease. "Four were common for local/cachexia (C1R, PRKCG, ELANE, SOST: all oppositely regulated) and four for metastatic/cachexia (SERPINA6, PDGFRA, PRSS2, PRSS1: all consistently changed), suggesting that stage and cachexia status might be molecularly separable." (PMID 33334063, 2020).
cardiomyopathy (1 paper, 2016). A disease of the heart muscle or myocardium proper. "Some DEGs related to cytoskeleton organization (e.g. MTSS1, ACTN4 and CALD1), cardiomyopathy (e.g. ITGB5) and immune response (e.g. C1S and C1R), as well as some regulators (e.g. LEF1 and hsa-miR-33a) might play pivotal roles in the progression of DN." (PMID 27613243, 2016).
cataract (1 paper, 2023). Partial or complete opacity of the crystalline lens of one or both eyes that decreases visual acuity and eventually results in blindness. "Congenital cataract samples also demonstrated an upregulation of C4 proteins, while posterior polar cataracts presented upregulated C3 proteins and posterior polar C1r proteins." (PMID 37240389, 2023).
chronic kidney disease (1 paper, 2025). Impairment of the renal function secondary to chronic kidney damage persisting for three or more months. "Importantly, intrarenal complement gene expression (C1R, C1QB, C6, C9, C5, MASP2) predicts nonresponse to induction therapy, alluding to the potential pathogenic role of intrarenal complement gene expression in chronic kidney disease." (PMID 41031884, 2025).
colorectal cancer (1 paper, 2019). A primary or metastatic malignant neoplasm that affects the colon or rectum. "CSMD2 encoding a member of the C1r/C1s, Uegf, Bmp1 (CUB) and sushi multiple domain protein (CSMD) family – is a candidate TSG associated with colorectal cancer." (PMID 31200735, 2019).
Duchenne muscular dystrophy (1 paper, 2024). Duchenne muscular dystrophy (DMD) is a neuromuscular disease characterized by rapidly progressive muscle weakness and wasting due to degeneration of skeletal, smooth and cardiac muscle. "Most recently, both C1R and C1S subunits contribution to the development of Duchenne muscular dystrophy (DMD) by regulating innate immunity and inflammation has been studied." (PMID 39009419, 2024).
Fanconi anemia (1 paper, 2022). Fanconi anemia (FA) is a hereditary DNA repair disorder characterized by progressive pancytopenia with bone marrow failure, variable congenital malformations and predisposition to develop hematological or solid tumors. "We found that the lower mRNA expressions of C1R, C6, C7, CFP, and CFHR3 were correlated with pathways like Fanconi anemia pathway, cell cycle, MicroRNAs in cancers, and so on." (PMID 34813686, 2022).
geographic atrophy (1 paper, 2022). "The complement pathway component C1R was also highly upregulated in the geographic atrophy RPE cells, as observed in other retinal dystrophies’ RPE cells." (PMID 35882847, 2022).
Hypertension (1 paper, 2015). The presence of chronic increased pressure in the systemic arterial system. "Mφs were recruited into the aortic adventitia soon after blood-pressure elevation and secreted complement C1q, which activated β-catenin signalling with C1r and C1s and induced proliferation of VSMCs, resulting in progression of hypertension-induced pathological arterial remodelling." (PMID 25716000, 2015).
Insulin resistance (1 paper, 2019). Increased resistance towards insulin, that is, diminished effectiveness of insulin in reducing blood glucose levels. "protein C receptor, endothelial (EPCR) (PROCR), C1R, CFI, PLAT, C4BPB, and CFB are novel biomarkers for the development of insulin resistance." (PMID 30678306, 2019).
ischemic heart disease (1 paper, 2024). "The results of the mediated MR analyses indicate that potassium may reduce the risk of ischemic heart disease by influencing the expression of the plasma proteins BDH2 and C1R." (PMID 39691718, 2024).
leukemia (1 paper, 2015). A malignant (clonal) hematologic disorder, involving hematopoietic stem cells and characterized by the presence of primitive or atypical myeloid or lymphoid cells in the bone marrow and the blood. "It is unclear if C1R plays a functional role for leukemia development or if it is differentially methylated in leukemia initiating cells, but this is not a prerequisite for biomarkers." (PMID 26539253, 2015).
Leukoencephalopathy (1 paper, 2019). This term describes abnormality of the white matter of the cerebrum resulting from damage to the myelin sheaths of nerve cells. "The observation that periodontal Ehlers–Danlos syndrome caused by missense mutations in C1R is consistently associated with a leukoencephalopathy opens a new pathogenic link between the classical complement pathway, connective tissue, brain small vessels, and brain white matter abnormalities." (PMID 30535813, 2019).
leukopenia (1 paper, 2025). "Building upon the multilayer module network constructed, we identified key targets of CB herbs in the treatment of leukopenia, including TGFB1, C1R, CD4, and HMGB1, which regulate leukopenia through signal transduction, cellular process, and immune response." (PMID 40890790, 2025).
melanoma (1 paper, 2022). A malignant, usually aggressive tumor composed of atypical, neoplastic melanocytes. "Therefore, we investigated the expression of complement components C1R, C1S, C5, and C3 by qRT-PCR in MCs treated with melanoma cell-derived conditioned medium." (PMID 35669782, 2022).
Portal vein thrombosis (1 paper, 2021). Thrombosis of the portal vein and/or its tributaries, which include the splenic vein and the superior and inferior mesenteric veins. "Histological analysis in H&E confirmed portal vein thrombosis and immunohistochemical analysis was strongly positive for C1r, C4d and ICAM." (PMID 34073536, 2021).
prostate carcinoma (1 paper, 2020). A carcinoma that arises from epithelial cells of the prostate gland. "Interestingly, three components of the complement system, namely C3, C1R, and CFB, also showed a significant upregulation after interaction with the metastatic cell line MDA-MB231 and two of them (C3 and C1R) could be validated in the prostate cancer model." (PMID 31963450, 2020).
psoriasis (1 paper, 2018). An autoimmune condition characterized by red, well-delineated plaques with silvery scales that are usually on the extensor surfaces and scalp. "More importantly, the absence of specific associated components, such as the immune complexes C1r-C1s-C1-INH and C3bBbP, in the plasma of psoriasis patients with elevated C5b-9 levels is a direct evidence that systemic complement is not activated in psoriasis." (PMID 29713318, 2018).
psychological distress (1 paper, 2018). "By interpreting the score plot in combination with the loading plot for HADSCWP, three of the proteins with highest VIP value were positively associated with psychological distress: complement factor B, complement C1r subcomponent, and hemopexin." (PMID 30555396, 2018). "Psychological distress in CWP was associated with plasma proteins related to immunity response and iron ion metabolism such as complement factor B, complement C1r subcomponent, and hemopexin." (PMID 30555396, 2018).
pulmonary embolism (1 paper, 2023). The obstruction of the pulmonary artery or one of its branches by an embolus, sometimes associated with infarction of the lung. "This study aimed to investigate the potential application of plasma signal peptide‐complement C1r/C1s, Uegf and Bmp1‐epidermal growth factor domain‐containing protein 1 (SCUBE‐1) as a biomarker in the diagnosis of pulmonary embolism (PE)." (PMID 36748401, 2023).
relapsing fever (1 paper, 2023). Relapsing fever is an infection caused by bacteria of the genus Borrelia, excluding those responsible for Lyme disease belonging to the Borrelia burgdorferi complex. "The C1r-inhibitory activities of a third ortholog termed FbpC, which is found exclusively in relapsing fever–causing spirochetes, remains unknown." (PMID 37380082, 2023). "Some of these complement evasion lipoproteins act as highly specific inhibitors of complement proteases, including a family of C1r inhibitors prototyped by B. burgdorferi BBK32 and the orthologous Fbp proteins of relapsing fever and B. miyamotoi spirochetes." (PMID 37380082, 2023).
renal cell carcinoma (1 paper, 2021). "C1q mediated recruitment of TAM: In renal cell carcinoma, tumor cells were shown to produce high levels of C1r, C1s, C4, and C3." (PMID 34572075, 2021).
sarcopenia (1 paper, 2024). Progressive decline in muscle mass due to aging which results in decreased functional capacity of muscles. "Our results support the determination of EV PF4 and C1R as plasma diagnostic biomarkers in sarcopenia and open the door to investigate the role of the content of these vesicles in the pathogeny of the disease." (PMID 39009419, 2024). "Moreover, PF4 and C1R proteins arise as promising diagnostic biomarkers for the identification of sarcopenia in routine clinical practice facilitating prevention and early and more effective interventions." (PMID 39009419, 2024). "Among the candidate proteins, PF4 and C1R showed the largest differences in concentration within sEVs between the sarcopenia and robust individuals." (PMID 39009419, 2024).